TNF (tumor necrosis factor)
Diseases named in the same sentence as TNF in open-access papers (continued):
Sharing a sentence is not in itself a finding about the gene and the disease.
Obesity (continued). "Data from animal and human studies have shown that obesity leads to a systemic proinflammatory state as indicated by higher plasma concentrations of various inflammatory markers, including CRP, interleukin 6 (IL-6), tumor necrosis factor α (TNF-α), and monocyte chemoattractant protein 1 (MCP-1)." (PMID 31192262, 2019). "This is consistent with previous studies showing that HFD-induced obesity could lead to significant increases in levels of lipid peroxidation products (HNE and malondialdehyde [MDA]) and TNF-α, as well as activation of microglia in the hippocampus of mice and rats." (PMID 31546722, 2019). "Also, in an animal model study, it was shown that TNFα expression in colorectal tissue was significantly higher in mice with obesity induced by improper diet than in a group without metabolic disorders." (PMID 31565100, 2019). "Conversely, TNF-α was positively related, and IL-6, leptin, insulin, total n-6, n-3 and n-6/n-3 PUFAs in whey breastmilk were negatively correlated to several infant growth measures in offspring of women without overweight or obesity." (PMID 31141526, 2019). "Despite the fact that our data do not identify obesity as an independent risk factor for JIA, they suggest a negative influence on disease activity at baseline and an unfavorable impact on the therapeutic response to conventional DMADs and anti-TNF drugs." (PMID 31249526, 2019). "Another recent publication reported that patients with metabolic diseases (obesity, type 2 diabetes, metabolic syndrome, cardiovascular disease, and nonalcoholic fatty liver disease) had a significant decrease in TNF-α plasma levels with CoQ10 supplementation but not CRP or IL-6." (PMID 31083534, 2019). "For TNFα and IL4, the primary contributing factor to population differences was higher obesity in AA women and higher education in EA women, respectively; whereas for IL1RA, obesity, education, and age at first childbirth were contributing factors to observed differences." (PMID 29879116, 2018). "Our data suggest that obesity could increase TNF‐α and CCR2 in the kidney, when hyperinsulinemia is not present." (PMID 29632818, 2018). "Our data were determined through modulation of TNF‐related inflammation in obesity rather than directly modifying monocytes, which may explain this discrepancy." (PMID 30548217, 2018). "Besides, US-FLI score was significantly correlated with TNF-α and M30 levels among children without obesity in this study." (PMID 30671426, 2018). "Though we had hypothesized that obesity would negatively impact response to anti-TNF therapy across all selected diseases, we did not observe such an association in patients with IBD." (PMID 29771924, 2018). "At this relatively early stage of obesity, however, there was no detectable increase in protein concentrations of inflammatory cytokines in the extracellular fluid of BM including IL-1b, interleukin 6 (IL-6) or tumor necrosis factor (TNF)." (PMID 29453396, 2018). "It has been suggested that IL-15 and aberrant leptin secretion with obesity might instigate an adipose-specific NK-cell expansion and activation in response to high-fat diet overfeeding, stimulating NK-cell IFN-γ, TNF-α, and MCP-1 production, negatively impacting whole-body insulin sensitivity." (PMID 29479350, 2018). "Recent studies have confirmed that obesity is a state of low-grade chronic inflammation that is characterised by increased concentrations of C-reactive protein (CRP), tumour necrosis factor-alpha (TNF-α), interleukin-6 (IL-6), and other inflammatory markers in the blood." (PMID 30914847, 2018). "In addition, an increase of the immunoregulatory CD56bright NK cell number may lead to an enhanced secretion of cytokines, like TNF-α and IFN-γ, and therefore potentially contribute to the obesity-induced low-grade inflammation state." (PMID 29560551, 2018).
Obesity (continued). "Pro-inflammatory cytokines such as IL-1, IL-6, and TNF-α produced by adipose tissue or in response to stress can activate the hypothalamic-pituitary-adrenal (HPA) axis; hence the relationship among obesity, systemic inflammation, and stress reactivity is cyclical in nature." (PMID 30538987, 2018). "We did not observe obesity-related differences in TNFα production by macrophages (data not shown)." (PMID 28800775, 2017). "In contrast, in obesity, interferon (IFN)-gamma and lipopolysaccharide (LPS) drive the polarization of recruited monocytes toward inflammatory M1-type macrophages and produce a large amount of nitric oxide by expressing inducible nitric oxide synthase (Inos), TNF-α, IL-6, IL-1β, IL-12, and MCP-1." (PMID 28692672, 2017). "It still remains unclear that whether elevations of inflammatory markers like tumor necrosis factoralpha (TNF-α), interleukin-6 (IL-6) and high sensitive C-reactive protein (hs-CRP) are related to PCOS or are a function of obesity, abdominal adiposity, or both." (PMID 28042411, 2017). "Moreover, it has been proposed that locally produced and secreted TNF-α by skeletal muscle cells, rather than circulating TNF-α, plays an important role in obesity-induced insulin resistance in skeletal muscle." (PMID 28099528, 2017). "Mechanistically, the obesity-related inflammation includes mTOR, JAK, JNK, IKKβ, and PI3K/Akt signaling pathways involved in inflammation activation, which contribute to increased secretion of cytokines, such as TNF-α, IL-6, and resistin, and decreased secretion of adiponectin." (PMID 28182687, 2017). "Obesity leads to lipid accumulation and activates the c-Jun N-terminal kinase (JNK) and nuclear factor-kappa B (NF-κB) signaling pathways, which consequently increase production of pro-inflammatory cytokines, such as tumor necrosis factor-alpha (TNF-α) and interleukin-6 (IL-6)." (PMID 29037210, 2017). "On the other hand, there have been indications that obesity-induced increases in TNF-α levels in WAT are not due to adipocytes but rather to increased expression by infiltrating macrophages, based on an experiment that cocultured adipocyte and macrophage cell lines." (PMID 28168013, 2017). "However, TNF-α is found to be overproduced not just in rheumatic diseases but in obesity, insulin resistance/metabolic syndrome, T2DM, and arthrosclerosis as well." (PMID 29721512, 2017). "Furthermore, TNFα and JNK play central roles in obesity and IR." (PMID 28134848, 2017). "Furthermore, a strong link exists between obesity and altered glucose metabolism, and pro-inflammatory markers such as C-reactive protein (CRP), interleukin-6 (IL-6) and tumour necrosis factor alpha (TNF-α)." (PMID 28193219, 2017). "However, this increase in their obesity status was not accompanied by an increase in circulating TNF-α levels." (PMID 27736740, 2016). "TNFα at high concentration may activate both TNFR1 and TNFR2, with effects of TNFR1 concealed by that of TNFR2, rending increased BAT thermogenic activity and obesity." (PMID 26903879, 2016). "This complex relationship between obesity and BMD could be explained by the effect on bone of a series of adipokines and cytokines secreted by adipose tissue, such as leptin, resistin, adiponectin, interleukin 6, and tumor necrosis factor-alpha." (PMID 27809297, 2016). "Although this is consistent with the adipose tissue expandability hypothesis, we also noted that there was no increase in circulating TNF-α as a marker of inflammation; hence, avoiding the inflammatory consequences of obesity might be equally important." (PMID 27736740, 2016). "Furthermore obesity as well as STEMI is considered a low-grade inflammatory state, as demonstrated by increased levels of the pro-inflammatory cytokines interleukin-6 and tumor necrosis factor-alpha, and acute phase proteins such as C-reactive protein." (PMID 26162888, 2015).
Obesity (continued). "The normal physiological effect of leptin on the regulation of TNF-α expression seems to be suppressive, but the hyperleptinemic condition and leptin resistance may both contribute to the rise of TNF-α in the adipose tissue in obesity." (PMID 25762868, 2015). "In addition, obesity significantly increased plasma TNF-α, PAI-1 and resistin levels in ApoE-/- mice but not in ApoE-/-TSP1-/- mice." (PMID 25803585, 2015). "Similarly, Carter reported that obesity induced insulin resistance was not accompanied by changes in TNF mRNA expression in neck SAT." (PMID 25938677, 2015). "They become the main source of proinflammatory cytokines such as tumor necrosis factor-α (TNF-α) and interleukin (IL)-6, and the chemokine monocyte chemoattractant protein-1 (MCP-1) that is elevated in both the adipose tissue and plasma of mice with diet-induced obesity." (PMID 26516917, 2015). "Moreover, obesity is associated in some studies with an increased risk of rheumatic diseases; and recent reports have showed a negative association between high BMI and response to anti-TNF agents in both RA and SpA, suggesting that fat mass may affect the response to biologic agents." (PMID 25426122, 2014). "Obesity did not induce significant differences in TNF-α and MCP-1 concentrations in parous mice." (PMID 25354395, 2014). "However, TNFα−/− and WT mice had no tendency of obesity on a chow diet, even at 6-month-old (data not shown)." (PMID 24522555, 2014). "Indeed, exposing macrophages and adipocytes to varying concentrations of palmitate, the most abundant circulating SFA in obesity, elicits a TLR4 dependent pro-inflammatory response characterized by increased NF-κB and JNK activation with resultant enhanced TNF-α cytokine secretion in vitro." (PMID 23675368, 2013). "In this context, the finding that tumor necrosis factor-α (TNF-α) and IL-6 are overexpressed in the adipose tissue of obese mice and humans and when administered exogenously leads to insulin resistance, provided the first clear link between obesity, diabetes, and chronic inflammation." (PMID 24151494, 2013). "While we did not observe any group differences in leptin, MCP-1, and TNF-α, all of which are considered to be important markers of inflammation in obesity, we did observe elevated F4/80 mRNA in WAT only in the HF-SED group compared to HF-EX and chow-fed groups." (PMID 23319832, 2012). "Obesity can induce increased c-Jun N-terminal kinase (JNK) activity which is activated in response to inflammatory cytokines, free fatty acids, activated NF-κB, and inflammatory mediators, including TNF-α and IL-6, and may contribute to insulin resistance." (PMID 23213270, 2012). "For the TNF-α-308G/A polymorphism, we referred to the analyses that the association of gender might have an influence upon the AMI onset in advance because obesity might not be involved." (PMID 22408428, 2012). "Other adipokines such as resistin, visfatin, vaspin, omentin, serum-retinol-binding protein (RBP)-4, chemerin, interleukin (IL)-6, plasminogen activator inhibitor (PAI-1), tumor necrosis factor (TNF), alpha, serum amyloid A, and angiotensinogen may have a role in obesity and T2D." (PMID 22619730, 2012). "Other effects of exercise that may affect obesity beyond energy expenditure include: 1) increased brain BDNF levels, 2) decreasing plasma and pancreatic β-cell content of IL-6 and TNF-α, 3) increasing parasympathetic tone, and 4) anti-inflammatory effects of exercise." (PMID 22808000, 2012). "As these horses were not obese, the higher TNF concentrations suggest high glycemic diets might promote inflammation independent of obesity." (PMID 26486919, 2012). "Obesity, particularly visceral adiposity, is accompanied by chronic low-grade inflammation, indicated by increased serum levels of inflammatory markers such as C-reactive protein (CRP), tumor necrosis factor-α (TNF-α), and interleukin-6 (IL-6) of obese patients." (PMID 22375203, 2010).
Obesity (continued). "Basal TNFα levels were low in all animals, not dependent on obesity and not altered upon wounding." (PMID 21318183, 2010). "While the hepatic upregulation of these actors could be important in the progression of liver complications, the real contribution of these proteins for inflammatory cells recruitment into the liver has to be determined, since systemic levels of IL6, TNFα, IP10 and MCP1 are dependent on obesity." (PMID 21042596, 2010). "In contrast, pathophysiological states—including sedentary lifestyle, obesity, chronic inflammation, and glucocorticoid excess—favor a shift toward a proinflammatory and catabolic myokine profile, characterized by increased levels of myostatin, non-muscle-derived IL-6, and TNF-α." (PMID 40648864, 2025). "However, a recent study has reported that higher chemerin levels are not correlated with increased chemerin bioactivity, even though increased chemerin secretion may be induced by TNF-α, a pro-inflammatory cytokine, which is highly expressed by PRAT in obesity." (PMID 40227577, 2025). "In addition, many studies have shown that pro-inflammatory cytokines, such as tumor necrosis factor (TNF), interleukin 6 (IL-6), IL-1β, and interferon-gamma (IFN-γ), can influence insulin resistance, adipose tissue inflammation and regulate obesity-related metabolism." (PMID 40931194, 2025). "Baseline mean TNF-α concentrations of 1.8 ± 8.5 pg/mL in the study population were similar to median concentrations observed in subjects without (1.6 (1.2–2.1 pg/mL)) and with obesity (1.8 (1.4–2.2 pg/mL)) in a study of cytokine profiles by BMI in individuals who were matched for age and gender." (PMID 39683518, 2024). "Interestingly, obesity, coupled with other metabolic diseases, is characterized by chronic inflammation and elevated levels of inflammatory chemokines and cytokines, such as monocyte chemoattractant protein-1 (MCP-1) and tumor necrosis factor-α (TNF-α), in adipose tissue, the liver, and/or blood." (PMID 39595979, 2024). "Additionally, the efficacy and retention rates of secukinumab do not appear to be negatively affected by obesity, with some studies reporting a positive impact on clinical outcomes, contrary to that described with other approaches, such as tumor necrosis factor blockade." (PMID 37533855, 2023). "Moreover, TNF-α positively regulates PAI-1 expression which, in turn, induces insulin resistance and metabolic abnormalities in liver during proinflammatory processes, thus suggesting a common link between TNF-α, insulin resistance, and elevated PAI-1 in obesity." (PMID 38256882, 2023). "In addition, the mRNA expression of pro-inflammatory cytokines TNFα, IL-6, and IL-1β was significantly higher in HFD-fed animals in comparison to STD-fed animals, suggesting that type I gustatory cells can be differentiated into M1-like phenotype of macrophages in obesity." (PMID 37373472, 2023). "In 2021, Sarkar and Thirumurugan demonstrated the regulation of RNF213 through the TNFα/PTP1B signaling pathway and PPARγ, suggesting that RNF213, similar to TNFα, may constitute an additional connection between MMA, inflammation, insulin resistance, and obesity." (PMID 37273690, 2023). "In addition, antibody neutralization of CD44 reduces obesity-induced adipose tissue inflammation, as demonstrated by decreased expression of immune cell markers (CD68, F4/80, CD3e, and CD19), proinflammatory cytokines (TNF-α, IL-1β, IL-6, and IFN-γ), and monocyte chemoattractant protein-1 (MCP-1)." (PMID 37383542, 2023). "For that purpose, group of 45 children with obesity (OB) and group of 45 age‐matched children without obesity (CG) were examined in terms of serum levels of miR‐27a and biochemical parameters: fasting blood glucose, adiponectin, leptin, resistin, subfatin, visfatin, and TNF‐α, IL‐6." (PMID 34918493, 2022). "Also we did not measure sarcopenic obesity related pro-inflammatory cytokines such as interleukin 6 and tumor necrosis factor which could lead IR." (PMID 34983489, 2022).
Obesity (continued). "A greater chance of obesity was observed in patients who had leptin AA/AG haplotypes (rs7799039) (OR 3.9; 95% CI 1.4–12.1; p=0.003) and adiponectin (rs17300539) (OR 8.4; 95% CI 1.8–72.2; p=0.001) when compared to GG haplotypes, but not significant for patients’ TNF-α haplotypes." (PMID 35703718, 2022). "Numerous factors could elucidate the relationship between obesity and anxiety, one of which is immune-inflammatory stimulation, as both conditions increase inflammatory biomarkers, such as C-reactive protein (CRP), interleukin-6 (IL-6) and tumour necrosis factor-alpha (TNF-α)." (PMID 33962601, 2021). "Obesity-driven BRCA1 upregulation is not able to be explained by DNA methylation (EPIC array) or by short-term treatment of chorionic villous explants at 2.5% oxygen with tumor necrosis factor α (TNF-α) (50 mg/mL), leptin (100 mg/mL), interleukin 6 (IL-6) (100 mg/mL), or high glucose (25 nM)." (PMID 31940810, 2020). "Thus, we speculate that simultaneously increased plasma levels of free fatty acid, TNF-α and MIP-1α/CCL3 may have the potential to induce significant pathophysiological changes in the adipose tissue compartment in obesity, including changes in insulin sensitivity and lipid metabolism." (PMID 33050324, 2020). "So far, characterization of the avian TNF and leptin has surprisingly revealed a very low or absent mRNA expression in adipose tissue as characterized under a variety of physiological conditions related to obesity, body growth, reproduction efficiency and feeding regimen." (PMID 31514326, 2019). "Although the mechanism for the increase in circulating zonulin in obesity is not fully eluded, it is proposed that inflammatory cytokines such as TNFα, and IL-6 produced by adipose tissue may trigger zonulin release, further increasing intestinal permeability, allowing more LPS into circulation." (PMID 31114691, 2019). "In addition, blood-brain barrier (BBB) permeability was increased in a model of obesity-induced by HFD and also aggravated cognitive deficit by increasing the exposure of the brain to various cytokines, including LPS, IL-1β, IL-6, and tumor necrosis factor alpha (TNFα)." (PMID 29316965, 2018). "Moreover, increased intestinal inflammatory gene expression of TNF-α, IL-6, ICAM and PTGS-2 was found in insulin-resistant obese patients compared to non-insulin-resistant obese patients, suggesting that intestinal inflammation is involved in diabetes during obesity." (PMID 27620343, 2017). "MCT1 haploinsufficient (MCT1+/−) mice are resistant to the development of obesity and the appearance of hepatic steatosis when fed a high fat diet as well as to the development of chronic hepatic inflammation as indicated by the absence of TNFα mRNA induction under HFD." (PMID 29092796, 2017). "Therefore, in the obesity-related cancer environment where many cytokines show altered profiles, angiogenesis factors (i.e., EGF, VEGF, and PAI-1) and inflammatory mediators (i.e., IL-1, IL-6, TNF-α, and leptin) are thought to cultivate a favorable environment for neoplastic cell growth." (PMID 26794215, 2016). "However, in four studies, TNF-α was comparable among CP patients with and without obesity." (PMID 27795608, 2016). "Therefore, as the low-grade inflammation seems to be determinant in the advent of obesity-related diseases such as type 2 diabetes and AVD, further studies are needed in order to determine the role of IL-12 in the production of IFN-γ and TNF-α in obese subjects." (PMID 23533314, 2013). "Thus, the degree of obesity as well as the presence or absence of TNFα may be of importance in determining the protective effects of leptin." (PMID 23125848, 2012). "Individuals with PCOS and a normal weight have also been found to have higher circulating levels of TNF-α (tumor necrosis factor-alpha) compared to healthy controls, supporting evidence that PCOS is a pro-inflammatory state, even in the absence of obesity." (PMID 41295220, 2025).